HMOX1 (heme oxygenase 1)
Diseases named in the same sentence as HMOX1 in open-access papers (continued):
Sharing a sentence is not in itself a finding about the gene and the disease.
asthma (continued). "We identified HMOX1, ITGAM, SFTPD and ADAM17 as the top novel targets for asthma which need to be validated experimentally whereas IL-18, TNF and VEGFA as the strongest therapeutic targets to investigate further for clinical benefit." (PMID 37735578, 2023). "Inter alia, enhanced expression of HMOX1 in animal models of inflammatory bowel disease (IBD) and asthma was observed to attenuate symptoms of the diseases by inhibition of Th17 responses." (PMID 28931834, 2017). "Genetic model distributions of HMOX1 gene rs2071747, CAT gene rs1049982, EPHX1 gene rs41266231, rs1051740, rs2234922 did not significantly differ between the asthma group and the control group." (PMID 40433469, 2025).
glioma (74 papers, 2013 to 2025). A benign or malignant brain and spinal cord tumor that arises from glial cells (astrocytes, oligodendrocytes, ependymal cells). "Our study elucidated an intricate association between SPP1/HMOX1 and multiple co‐expressed proteins in glioma, highlighting the potential role of SPP1/HMOX1 in regulating cell cycle and growth via the PI3K/AKT, JAK–STAT and syndecan 1 signalling pathways." (PMID 40495644, 2025). "Overall, the findings demonstrated that SPP1/HMOX1 were associated with poor overall survival in glioma patients, indicating their potential as clinical prognostic and therapeutic targets of oncolytic virus treatment." (PMID 40495644, 2025). "The results from GSEA enrichment indicated that elevated expression of SPP1/HMOX1 was strongly associated with glioma malignancy." (PMID 40495644, 2025). "The expression levels of SPP1/HMOX1 were significantly increased in glioma and associated with histological classifications and WHO grades." (PMID 40495644, 2025). "As high‐grade gliomas overexpressing SPP1/HMOX1 is associated with tumour progression and increased malignancy grade, genes co‐expressed with SPP1 and HMOX1 appear to be strongly associated with glioma development." (PMID 40495644, 2025). "The increased HMOX1 in a mouse model reduced the neuronal cell death induced by oxidative stress; however, excessive activation of HMOX1 can cause glioma cell death." (PMID 36689408, 2023). "Moreover, SPP1 and HMOX1 are directly associated with 20 key hub genes and play roles in regulating tumour progression in glioma." (PMID 40495644, 2025). "In addition, the elevated SPP1 and HMOX1 expression levels were found to be associated with more advanced histological subtypes of glioma, specifically when comparing GBM to astrocytoma, oligodendroglioma and oligoastrocytoma (p < 0.001)." (PMID 40495644, 2025). "Considering that patients with lower HMOX1 expression had lower TIDE score and showed higher response rate to immunotherapy, we conclude that HMOX1, as well as HMOX1-based risk signature, is capable for predicting the immunotherapy efficacy in lower grade gliomas." (PMID 34858984, 2021). "The current study is the first to demonstrate that SPP1 and HMOX1 downregulation in glioma cells infected with VSV‐M51 reveals a potential mechanism whereby VSV‐M51 infection modulates glioma." (PMID 40495644, 2025). "We discovered that PFKFB4 and HMOX1 control glioma’s growth, migration, invasion, and malignancy by studying apoptotic genes and others." (PMID 40739397, 2025). "GSEA analysis revealed the activation of cancer cell proliferation, EMT and tumour metastasis in the SPP1/HMOX1 overexpression group compared to the control group, indicating potential regulatory roles in glioma progression." (PMID 40495644, 2025). "The significant elevated expression of SPP1 and HMOX1 was detected in the samples diagnosed with classified as WHO G4/G3 gliomas in comparison to those with G2 glioma tissues (p < 0.001)." (PMID 40495644, 2025). "qPCR and HPA analysis were utilised to assess the mRNA/protein levels of SPP1 and HMOX1 in glioma tissues." (PMID 40495644, 2025). "In summary, the study identified that oncolytic virus VSV‐M51 treatment downregulated SPP1/HMOX1 expression in glioma cells." (PMID 40495644, 2025). "The data revealed that high SPP1/HMOX1 expression is positively related to patient age, IDH WT status, 1p/19q codeletion, and primary treatment outcome, suggesting that SPP1 and HMOX1 play crucial roles in the progression of glioma (p < 0.001)." (PMID 40495644, 2025). "Further, in‐depth experimental validation studies are warranted to elucidate the mechanism of SPP1/HMOX1‐involved signalling pathways in glioma, and also to study their possible role and interrelation in cell migration and tumour metastasis." (PMID 40495644, 2025).
glioma (continued). "In vitro analyses using glioma cell lines engineered to express IDH1 mutations demonstrated elevated levels of ferrochelatase (FECH) and heme oxygenase-1 (HO-1), enzymes involved in heme metabolism." (PMID 41008917, 2025). "Our results emphasised the importance of SPP1 and HMOX1 as novel targets for oncolytic virotherapy intervention, holding promise for glioma treatment." (PMID 40495644, 2025). "We subsequently evaluated the mRNA expression in a cohort of 20 glioma tissues using RT‐qPCR and found that SPP1 or HMOX1 was significantly overexpressed in glioma compared with non‐tumour tissues (p < 0.001)." (PMID 40495644, 2025). "This study also examined the roles of SPP1 and HMOX1, alongside the in‐depth regulatory mechanisms in glioma." (PMID 40495644, 2025). "Glioma patients exhibiting high levels of HMOX1 expression had a significantly shorter OS compared to those with lower HMOX1 expression (p < 0.001)." (PMID 40495644, 2025). "Each one of the two correlation coefficients manifested that both SPP1 and HMOX1 were consistently co‐expressed with 20 genes in glioma samples, such as VAMP8, RAC2, MSR1, CAPG and FBP1." (PMID 40495644, 2025). "To evaluate the prognostic significance of SPP1/HMOX1 overexpression in glioma specimens, we conducted Kaplan–Meier survival analysis." (PMID 40495644, 2025). "In conclusion, dysregulated SPP1/HMOX1 expression was strongly related to glioma WHO grades and worse outcomes, providing deeper insights into glioma therapeutic targets and oncolytic virus‐based treatments." (PMID 40495644, 2025). "Analysis of gene/protein expression levels and clinical significance was performed to identify the roles of SPP1/HMOX1 using TCGA‐glioma data." (PMID 40495644, 2025). "SPP1/HMOX1 was involved in influencing glioma cell motility through the PI3K/AKT, JAK–STAT and syndecan 1 signalling pathways." (PMID 40495644, 2025). "To delve deeper into the mechanisms underlying gene interactions, we employed a single‐gene differential expression analysis to determine potential co‐expressed genes that strongly correlated with SPP1/HMOX1 in glioma." (PMID 40495644, 2025). "The data from TCGA analysis showed that the expression levels of SPP1/HMOX1 were higher in WHO Grade IV (GBM) tissues than in the low‐grade glioma (LGG) group." (PMID 40495644, 2025). "To elucidate the molecular mechanism by which SPP1/HMOX1 contribute to glioma development, we utilised TCGA‐GBMLGG data cohorts to carry out GSEA analysis." (PMID 40495644, 2025). "The GSE166914 dataset was analysed to examine the SPP1 and HMOX1 expression after VSV‐M51 infection in glioma." (PMID 40495644, 2025). "In gliomas, a paradoxical phenomenon occurs in which HMOX1 is overexpressed and correlated with worse survival, promoting glioma cell proliferation." (PMID 39857625, 2024). "In particular, HMOX1, which was upregulated 28 times in ferroptotic glioma cells in our study, is known to play a dual role in cancers." (PMID 39857625, 2024). "Single‐cell analysis of data from purified malignant glioma cells showed that HMOX1, LTF, and STEAP3 were predominantly expressed in mesenchymal‐like cell clusters facilitating intratumoral mesenchymal shift over time." (PMID 37545464, 2024). "AT-101, a natural compound from cotton seeds, induced excessive mitophagy in glioma cells by upregulating the expression of heme oxygenase 1 (HMOX1) and the mitophagy receptors BNIP3 and BNIP3L." (PMID 37794028, 2023). "Because HMOX1 activity stimulates angiogenesis, this enzyme is a suitable indicator of glioma neovascularization." (PMID 36142793, 2022). "The analysis of the microarray dataset from clinical biopsies showed that HMOX1 expression levels significantly increase in glioma grade IV brain biopsies when compared to grade I, II, and III." (PMID 34572050, 2021).
glioma (continued). "We observed that HMOX1 expression was increased in lower grade gliomas at both tissue and single-cell levels, and such increase was associated with worse OS, DSS, and PFI in patients with LGG." (PMID 34858984, 2021). "Second, only one cohort with single-cell sequencing data was employed to evaluated the functions of HMOX1 in glioma." (PMID 34858984, 2021). "Using our own samples, we validated that grade III gliomas had higher HMOX1 protein expression compared with grade II gliomas." (PMID 34858984, 2021). "In our study, we employed data from independent cohorts to explore the expression profile of heme oxygenase-1 in glioma." (PMID 34858984, 2021). "Currently, several clinical trials are attempting to explore the clinical benefits of targeting HMOX1 (or related molecules) in the treatment of lower grade gliomas and other solid cancers." (PMID 34858984, 2021). "We comprehensively analyzed two independent glioma cohorts, as well as samples from our institution, to explore the HMOX1 profiling in the context of gliomas." (PMID 34858984, 2021). "HMOX1 and the risk signature are reliable predictors of LGG prognosis, and targeting HMOX1 will help clinicians optimize the management of lower grade glioma patients in future preclinical and clinical practice." (PMID 34858984, 2021). "And in both tumor tissues and cell lines, HMOX1 was found to be elevated in glioma tissues and cells (U-138 MG and U-87 MG)." (PMID 34858984, 2021). "While arsenic trioxide increased the production of ROS in glioma cells, it also increased the expression of heme oxygenase-1 (HO-1) and its upstream effector Nrf2." (PMID 32983240, 2020). "Whereas HA appears to be an upstream regulator of OPN in gliomas, heme oxygenase 1 (HO-1) appears to be a downstream effector of OPN contributing to cell movement." (PMID 33203146, 2020). "We found only one proinflammatory gene, HMOX1, being downregulated in glioma cells upon treatment with ISCADOR Qu, Aviscumine, or native ML-1." (PMID 30224928, 2018). "Furthermore, CCK‐8 and flow cytometry also show the anti‐tumour effect of silencing HMOX1 in glioma (p < 0.05, p < 0.01, p < 0.001)." (PMID 40495644, 2025). "Elevated levels of SPP1/HMOX1 were related to poor prognosis in glioma." (PMID 40495644, 2025). "Furthermore, immunohistochemical analysis showed that SPP1 and HMOX1 were significantly upregulated in glioma tissues compared to cerebral cortex tissues." (PMID 40495644, 2025). "SPP1 and HMOX1 have the potential to be biomarkers for the diagnosis and prognosis of glioma." (PMID 40495644, 2025). "Silencing SPP1/HMOX1 suppressed glioma cell proliferation and promoted apoptosis." (PMID 40495644, 2025). "Moreover, the co‐expressed genes with SPP1/HMOX1 were subjected to a GSEA analysis in order to explore regulatory signalling pathways activated by SPP1/HMOX1 in glioma." (PMID 40495644, 2025). "To evaluate the potential role of SPP1/HMOX1 in promoting tumour progression in glioma, we examined whether silencing SPP1 and HMOX1 affects glioma cell viability and apoptosis." (PMID 40495644, 2025). "Furthermore, our findings revealed a hallmark of the JAK–STAT signalling pathway (NES = 1.995, p = 0.011, FDR = 0.004) and the syndecan 1 pathway in gliomas expressing HMOX1 (NES = 2.405, p < 0.001, FDR < 0.001)." (PMID 40495644, 2025). "In vitro experiments showed higher expression levels of SPP1/HMOX1 in glioma tissues." (PMID 40495644, 2025). "Moreover, our data reveal that elevated levels of SPP1/HMOX1 are observed across different glioma histological types, with higher expression noted in high‐grade glioma patients compared to those with low‐grade glioma." (PMID 40495644, 2025). "Finally, the top three genes (STEAP3, LTF, and HMOX1) with the greatest importance were chosen as key prognostic IMRGs for gliomas." (PMID 37545464, 2024). "Low expression of GPX4 and high expression of HMOX1 were identified in DHA treated glioma cells." (PMID 36164395, 2022).
glioma (continued). "Further work is certainly imperative for the validation of HMOX1 functions in lower grade glioma." (PMID 34858984, 2021). "HMOX1 overexpression is observed in various solid malignancies, including bladder, breast, colon, glioma, lung, prostate, and gastric, cancers." (PMID 34858984, 2021). "Moreover, drug-induced mitochondrial dysfunction and heme oxygenase 1 (HMOX1) overactivation synergize to trigger lethal mitophagy in glioma cells, which is significantly blocked by silencing of the mitophagy receptors BNIP3 and NIX." (PMID 32671064, 2020). "Reports have shown that DMF exerted anti-inflammatory and prometabolic effects in a variety of cell types in primary astrocytes and C6 glioma cells by modifying glutathione (GSH) levels that can induce expression of the anti-inflammatory protein HO-1 (heme oxygenase-1)." (PMID 26090715, 2015). "Osteopontin has been described to regulate expression of heme oxygenase-1 in glioma cells." (PMID 24971311, 2014). "HMOX1 is a potential therapeutic target, it is over-expressed and facilitates angiogenesis in glioma and may influence the outcome of the disease." (PMID 25182732, 2014). "Moreover, a study demonstrated that baicalein inhibited ROS-mediated cytotoxic effects through the modulation of ERKs activation and the induction of heme oxygenase-1 (HO-1) protein expression on H2O2-induced rat glioma C6 cells." (PMID 24348193, 2013). "Furthermore, allograft inflammatory factor-1 (AIF-1) and heme oxygenase-1 (HO-1) can also be used to define a distinct subset of GAMs in rat and human gliomas." (PMID 23983766, 2013). "Upregulation of Bach1, a transcription factor regulating heme oxygenase-1 (HO-1) which catalyzes the breakdown of heme into iron, correlated with EMT and ferroptosis sensitivity in glioma cells, suggesting Bach1 as a potential marker of ferroptosis susceptibility in glioma patients." (PMID 39188677, 2024). "Similarly, survival probability in hepatocellular carcinoma was reliably predicted by a glioma prediction model (ACSL3, ACSL6, ACACA, G6PD, SLC1A5, SLC7A11 and VDAC2) and by a risk model with a strong overlap with the genes in the glioma models (G6PD, HMOX1, LOX, SLC7A11, STMN1/Stathmin 1)." (PMID 34926298, 2021). "Similarly, glioma tissue had elevated protein level of HMOX1 than normal cerebral cortex tissue." (PMID 34858984, 2021). "Our study proposed, for the first time, that SPP1/HMOX1 contributeso the activation of the PI3K/AKT, JAK–STAT and syndecan 1 signalling pathways, thereby maintaining the motility and malignancy of glioma cells." (PMID 40495644, 2025). "Our findings highlight the importance of SPP1/HMOX1 overexpression in glioma, suggesting a potential correlation between SPP1/HMOX1 expression and IDH status in glioma." (PMID 40495644, 2025). "The present study investigated the functional roles of SPP1 and HMOX1 in glioma and explored the downstream regulatory mechanism modulated by SPP1 and HMOX1." (PMID 40495644, 2025). "The data indicated that HMOX1, LTF, and STEAP3 had relatively higher expressions in glioma cells compared to most other cancer cell lines." (PMID 37545464, 2024). "HMOX1, LTF, and STEAP3 knockdown in glioma cells significantly reduced cell proliferation, colony formation, migration, and malignant invasion." (PMID 37545464, 2024). "After treatment with different doses of DFO and erastin, the transcriptional activities of HMOX1, LTF, and STEAP3 were reduced in both U87 and U251 glioma cells, indicating that these genes played a role in iron metabolism regulation." (PMID 37545464, 2024).
glioma (continued). "Significant upregulation of Dusp6 and Fli1 gene expressions and downregulation of Hmox1 and Jun gene expressions in BV2 microglia, 2 h post segregated coculture with C6 glioma cells, were confirmed by RT-qPCR analysis." (PMID 39019900, 2024). "Out of these NRGs, 19 NRGs (EGLN3, HILPDA, HMBS, HYOU1, BNIP3, etc.)were found to be enriched in glioma tissues while 13 genes (SLC4A1, IL6, EPAS1, ACE, HMOX1, etc.)were decreased compared to normal tissues." (PMID 37934582, 2023). "These nanoparticles exploit the high ROS gradient in the glioma microenvironment to trigger the selective binding of Au(I) to overexpressed TrxR, activating HMOX1-regulated noncanonical ferroptosis in glioma cells and leading to tumor suppression." (PMID 38962305, 2024). "These in vitro findings demonstrated that HMOX1, LTF, and STEAP3 could facilitate the malignant progression of glioma cells." (PMID 37545464, 2024). "HMOX1, LTF, and STEAP3 were identified as the most essential IMRGs in gliomas." (PMID 37545464, 2024). "Furthermore, the TCGA and CCLE data showed that STC1, HMOX1 and TGFB1 were obviously up‐regulated in most glioma cells." (PMID 31282108, 2019). "HMOX1 expression levels, when analyzed alone, was inversely correlated with glioma patient survival, although not highly significant." (PMID 31772153, 2019). "Notably, SPP1/HMOX1 and co‐expressed genes were related to activating the PI3K/AKT, JAK–STAT and syndecan 1 pathways in glioma, contributing to the tumour progression of glioma." (PMID 40495644, 2025). "However, the roles of SPP1 and HMOX1 in glioma are not yet understood and require further exploration." (PMID 40495644, 2025). "Furthermore, a negative relationship existed between HMOX1 expression and tumor purity in lower grade gliomas, as it positively correlated with stromal, immune, and ESTIMATE scores." (PMID 34858984, 2021). "In fact, we could recently show that HMOX-1 is induced after Gos-mediated mitochondrial dysfunction in non-GSC glioma cells and that this is accompanied by induction of BNIP3 and Nix (BNIP3L), leading to an autophagic type of cell death." (PMID 30871073, 2019). "However, the induction of mitophagy by FOXO3a may protect gliomas from TMZ-induced cytotoxicity; it has been suggested that early mitochondrial dysfunction and HMOX1 activation may synergize to trigger lethal mitophagy, contributing to the cell death of natural compound AT 101 in glioma cells." (PMID 37174088, 2023). "Limitations of the current study include the lack of data regarding the regulatory mechanism of SPP1 and/or HMOX1 in glioma cell growth, as well as not providing in‐depth profiling for SPP1 and/or HMOX1 in different histologic grades of LGG or GBM." (PMID 40495644, 2025). "CERES scores of 98.305% (58/59), 71.186% (42/59), and 45.763% (27/59) cells were negative in glioma cells after LTF, STEAP3, and HMOX1 knockout, respectively." (PMID 37545464, 2024). "However, previous studies of CAPG, FANCD2, HMOX1, HSPB1, RRM2, and STEAP3 did not develop any new clinical therapy in glioma." (PMID 36566214, 2022).